PPCS (phosphopantothenoylcysteine synthetase)
Description:
Catalyzes the second step in the biosynthesis of coenzyme A from vitamin B5, where cysteine is conjugated to 4'-phosphopantothenate to form 4-phosphopantothenoylcysteine. Has a preference for ATP over CTP as a cosubstrate.
Synonyms: FLJ11838; CMD2C
Tractability: Small molecule: a structure with a bound ligand is known; it has a high-quality binding pocket. PROTAC: ubiquitination databases record sites on it; its protein half-life has been measured.
Gene: Protein-coding gene on chromosome 1 (42,456,117 to 42,473,385, forward strand). Ensembl gene ENSG00000127125.
Subcellular location (Human Protein Atlas): Mitochondria
Pathways (Reactome):
Metabolism: Coenzyme A biosynthesis
Gene Ontology:
Molecular function: identical protein binding; phosphopantothenate--cysteine ligase activity; protein homodimerization activity
Biological process: acetyl-CoA biosynthetic process; coenzyme A biosynthetic process; heart process
Cellular component: catalytic complex; cytoplasm; cytosol; nucleus
Genetic constraint (gnomAD): Loss-of-function variants: 17 observed, 23.98 expected, observed/expected ratio (o/e) 0.71, 90% interval 0.48 to 1.06. The upper end of that interval is the gene's LOEUF score, 1.06, which puts it in group 4 of 6, group 1 being the genes least tolerant of losing a copy. Missense variants: 360 observed, 405.19 expected, observed/expected ratio (o/e) 0.89, 90% interval 0.81 to 0.97. Synonymous variants: 190 observed, 172.64 expected, observed/expected ratio (o/e) 1.1, 90% interval 0.98 to 1.24.
Homologues: Orthologues: chimpanzee PPCS (99% identical), macaque PPCS (98% identical), guinea pig PPCS (92% identical), pig PPCS (89% identical), rat Ppcs (88% identical), mouse Ppcs (87% identical), dog PPCS (86% identical), tropical clawed frog ppcs (63% identical), zebrafish ppcs (57% identical), Drosophila melanogaster Ppcs (39% identical), Caenorhabditis elegans Y71H2AM.6 (37% identical). Paralogues in human: CNIH3 (11% identical), CNIH2 (11% identical), CNIH1 (10% identical), CNIH4 (7% identical).
Diseases named in the same sentence as PPCS in open-access papers:
PPCS is named in the same sentence as 5 diseases in open-access papers, as found by Europe PMC text mining. Sharing a sentence is not in itself a finding about the gene and the disease. The quoted sentences say what the papers report.
dilated cardiomyopathy (3 papers, 2022 to 2023). Cardiomyopathy which is characterized by dilation and contractile dysfunction of the left and right ventricles. "A few years ago, a rapidly fatal dilated cardiomyopathy was linked to pathogenic variants in the second enzyme of the pathway (phosphopantothenoylcysteine synthetase, PPCS) with the discovery of three affected families." (PMID 36983025, 2023). "Moreover, these techniques to study the fly heart have been applied to establish genetic causality for dilated cardiomyopathy using fly models deficient for Phosphopantothenoylcysteine synthetase (PPCS) and transgenic flies that caried PPCS with patient variants." (PMID 37123266, 2023). "By contrast, PPCS deficiency manifests as dilated cardiomyopathy of variable severity (CMD2C, MIM #618189), with no NBIA-related phenotypes." (PMID 36475414, 2022).
cancer (1 paper, 2020). A tumor composed of atypical neoplastic, often pleomorphic cells that invade other tissues. "Especially, through this analysis, proteins (PPCS, PMP2, and TUBB) and metabolites (L-carnitine and PC-O (30:0)) related to the carnitine system involved in cancer plasticity were identified." (PMID 33228226, 2020).
PPCS also shares sentences with these, for which no sentence is quoted: coronary artery disease (1 paper); infection (1); myopathies (1).